CLDN1 (claudin 1)
Diseases named in the same sentence as CLDN1 in open-access papers (continued):
Sharing a sentence is not in itself a finding about the gene and the disease.
ovarian carcinoma (continued). "CLDN1 gene expression and methylation play an important role in ovarian cancer aggressiveness and this relationship may provide a new therapeutic target." (PMID 33828978, 2021). "For example, overexpression of miR-155 could prevent tumorigenesis in human ovarian cancer by downregulating CLDN1." (PMID 33024414, 2020). "For example, miR-155 functions as a tumor suppressor by targeting CLDN1 in ovarian cancer." (PMID 26067567, 2015). "Claudin-1 expression is suppressed by miR-155 in colorectal and ovarian cancer cells." (PMID 26061016, 2015). "CLDN1 has oncogenic activity in colon cancer, bladder cancer, lung cancer, gastric cancer, ovarian cancer, and melanoma, but functions as a tumor suppressor in colorectal cancer (CRC), and its expression was inversely correlated with prognosis and overall survival." (PMID 26067567, 2015). "The transcriptional increase observed in CLDN1 correlated with serous ovarian cancer after analysis with ovarian cancer patient profiles, suggesting that LPA may play a molecular role in plasticity of the histology of ovarian cancer." (PMID 19440550, 2009). "Importantly, previous studies indicated that reduced CLDN1 expression could inhibited ovarian cancer cells mobility and invasion in vitro and tumor growth in vivo." (PMID 34116704, 2021). "Conversely, silencing PABPC3 in cells resulted in increased CLDN1 levels, further suggesting that PABPC3 promotes ovarian cancer metastasis." (PMID 41249135, 2025). "In univariate analysis of COX proportional hazards regression, CLDN1 was a favorable factor for LUAD and STAD, but an unfavorable factor for LAML, ovarian cancer (OV) and thymoma (THYM)." (PMID 41461671, 2025). "Furthermore, CLDN1 regulation during ovarian cancer-initiating cell proliferation and invasion was shown to be mediated by miR-155, where the endogenous mature form of the latter may inhibit cancer-initiating cell growth via reducing CLDN1 expression by targeting its mRNA on the 3’-UTR." (PMID 36672179, 2023). "This study investigated the expression levels of AXL, GAS6, Claudin-1, and Cofilin-1, as genes involved in EMT in relation to clinicopathologic features in ovarian cancer patients." (PMID 31700829, 2019). "In NIH:OVCAR5 cells, both parental and N4-over cells had increased amounts of E-Cadherin, β-catenin, and claudin-1, compared to the knock-down cells, suggesting Nectin-4 plays a role in EMT and ovarian cancer progression." (PMID 28038455, 2017). "However, claudin-1, claudin-4, and claudin-10 have been shown to be differentially expressed during the EMT in oral lichen planus and ovarian carcinomas." (PMID 33193109, 2020). "The data suggest that transcriptional events mediated by LPA in the tumor microenvironment influence tumor progression through modulation of cell adhesion molecules like claudin-1 and, for the first time, report an LPA-mediated expression signature in ovarian cancer that predicts a worse prognosis." (PMID 19440550, 2009). "However, in contrast, overexpression of CLDN-1 has been observed in colon, nasopharyngeal, ovarian and oral squamous cell cancers, while CLDN-3 and -4 are highly overexpressed in ovarian cancer and upregulated in breast, gastric, pancreatic, prostate and uterine cancers." (PMID 31952355, 2020). "It was reported that N-cadherin or Claudin-1 promotes the migration of ovarian cancer cells without the induction of complete EMT, suggesting that other molecules might contribute to Numb-induced migration and invasion in lung SCC; such pathways were not assessed in the current study." (PMID 30034624, 2018). "Pairwise CLDN biomarker AUC comparisons (heatmap), across 12 tumor types (The Cancer Genome Atlas; TCGA data), showed that CLDN1 could readily distinguish colon from kidney, brain, lung, and ovary cancers, while both CLDN1 and CLDN4 (but not CLDN18) could distinguish brain from kidney cancer." (PMID 29050243, 2017).
ovarian carcinoma (continued). "In this study CLDN1 is elevated in serous EOC and sufficient to cluster ovarian tumor types, which suggests it, by itself, is an ovarian cancer-type biomarker but not a prognostic biomarker." (PMID 19440550, 2009).
pancreatic cancer (28 papers, 2007 to 2025). "Cldn1 KO in pancreatic cancer cell lines caused reduced cell proliferation, migration, and invasion, highlighting its role in promoting malignancy in pancreatic cancer cells." (PMID 40361399, 2025). "In pancreatic cancer, increased expression of claudin-1 was found to be associated with tumor aggressiveness." (PMID 34808689, 2022). "In pancreatic cancer (PC), increased expression of CLDN-1 was found to be associated with epithelial-mesenchymal transition." (PMID 31952355, 2020). "Our findings contradict those of a recent study, which reported that Cldn1 loss might promote pancreatic cancer progression." (PMID 40361399, 2025). "In pancreatic cancer, increased expression of Claudin-1 is associated with disease progression." (PMID 38782891, 2024). "Additionally, TNF-α–mediated CLDN1 expression is associated with increased proliferation of pancreatic cancer cells." (PMID 37318881, 2023). "This study suggests that Cldn1 loss could be associated with more aggressive cancer behavior, in contrast to our results showing that Cldn1 expression correlates with poor prognosis and enhanced malignancy in pancreatic cancer cells." (PMID 40361399, 2025). "Claudin-1, a tight junction protein influencing cellular functions in various cancers and considered a therapeutic target, has an unclear role in pancreatic cancer." (PMID 40361399, 2025). "This study establishes Cldn1 as a crucial contributor to the malignancy of pancreatic cancer through its involvement in cellular proliferation, migration, invasion, and chemoresistance." (PMID 40361399, 2025). "These indicate that Cldn1 contributes to the proliferation, migration, and invasiveness of pancreatic cancer cells." (PMID 40361399, 2025). "Claudin-1 knockout with CRISPR/Cas9 on poorly differentiated pancreatic cancer cell lines and a proteome analysis were performed to investigate the intracellular mechanisms of claudin-1." (PMID 40361399, 2025). "According to the data we examined, only PK45H was a poorly differentiated pancreatic cancer cell line overexpressing Cldn1." (PMID 40361399, 2025). "This is in concordance with recent findings illustrating the regulatory role of CLDN1 in the metabolism of pancreatic cancer cells, which in turn has a significant impact on their sensitivity to certain chemotherapies." (PMID 40943068, 2025). "The expression sites of Cldn1 were significantly altered in L- and H-PanIN and pancreatic cancer cells compared to those in normal ductal cells (p < 0.001, p < 0.001, and p < 0.001, respectively)." (PMID 40361399, 2025). "Western blot analysis revealed that PK45H cells exhibited the highest levels of Cldn1 among the poorly differentiated pancreatic cancer cell lines." (PMID 40361399, 2025). "Conversely, maintaining or restoring CLDN1 expression can impede invasion/metastasis of pancreatic cancer cells." (PMID 40687428, 2025). "This study assessed claudin-1 expression in resected pancreatic cancer samples, public databases, and cell lines." (PMID 40361399, 2025). "In this study, we aimed to elucidate the role of Cldn1 in pancreatic cancer by generating Cldn1-knockout (KO) clones using CRISPR/Cas9 and analyzing their cellular dynamics." (PMID 40361399, 2025). "The immunostaining of these pancreatic cancer tissues revealed that Cldn1 was highly expressed in the cytoplasm of some cancer cells and that Cldn1 was associated with a poor differentiation of cancer cells and poor prognosis in patients with PDAC." (PMID 40361399, 2025). "In pancreatic cancer, the expression of claudin-1 is increased, especially in metastatic tissues, there is a nuclear cytoplasmic membrane localization error." (PMID 36959784, 2023). "It has been demonstrated that CLDN1 downregulation in pancreatic cancer results in the phosphorylation of FAK and paxillin, which further promotes cell invasion, migration, and tumor metastasis." (PMID 36620607, 2022).
pancreatic cancer (continued). "In this study, C150 treatment resulted in increased expression of the epithelial markers ZO-1 and claudin-1 in pancreatic cancer cells, both of which are integral components of tight junctions in cells with an epithelial phenotype." (PMID 34976816, 2021). "Previous studies have shown that the decrease in the expression of ZO-1 and Claudin-1 accelerates the invasion and migration of pancreatic cancer via a ZEB1-dependent transcription." (PMID 34631521, 2021). "It is implied that CLDN1 immunophenotype is closely relevant to the malignant behavior of pancreatic cancer." (PMID 30519576, 2018). "For example, expression of claudin-1 was decreased in pancreatic cancer cell lines compared with that in normal human pancreatic duct epithelial cells, and its expression was observed in the cytoplasm in poorly differentiated pancreatic adenocarcinoma cells." (PMID 27641742, 2016). "TNFα increased Claudin 1 expression in human pancreatic cancer cells, and in airway smooth muscle cells." (PMID 22675434, 2012). "Knockdown of CLDN1 promotes stemness, migration, and invasion of pancreatic cancer cells." (PMID 41050411, 2025). "The tight junction protein claudin-1, known to influence cellular functions in various cancers and is considered a therapeutic target, remains unclear in pancreatic cancer." (PMID 40361399, 2025). "Furthermore, Cldn1 was highly expressed in the metastatic lymph nodes and neural invasion areas of pancreatic cancer cells." (PMID 40361399, 2025). "However, the specific functions of Cldn1 and its clinical significance in pancreatic cancer cells remain poorly understood." (PMID 40361399, 2025). "If such mechanisms can be clarified, it may be possible to reduce the aggressiveness of pancreatic cancer cells via the regulation of Cldn1." (PMID 40361399, 2025). "A deeper investigation into the specific functions and regulatory pathways of Cldn1 in pancreatic cancer is essential to resolve these conflicting observations and develop targeted therapies that could improve patient outcomes." (PMID 40361399, 2025). "Understanding the molecular mechanisms by which Cldn1 influences pancreatic cancer progression could provide critical insights into its potential as a therapeutic target." (PMID 40361399, 2025). "This discrepancy underscores the complexity of the Cldn1 role in pancreatic cancer." (PMID 40361399, 2025). "However, we observed high Cldn1 expression in a subset of pancreatic cancer cells, particularly in those with aggressive characteristics." (PMID 40361399, 2025). "Claudin-1, a tight junction protein, which is also present in the human intestine, is up-regulated in intestinal inflammation and plays a significant role in pancreatic cancer invasion; for this reason, it is useful as a biomarker during disease." (PMID 37175426, 2023). "TNF-a upregulates the expression of claudin-1 in pancreatic cancer by concentration dependence, leading to accelerated tumor cell proliferation.The region surrounding the CpG island of the CLDN1 promoter controls transcription through methylation to alter epigenetic regulation." (PMID 36959784, 2023). "The mechanism tying claudin expression to the aggressiveness of pancreatic tumors may be from the claudin-1-induced activation of mitogen-activated protein kinase 2 and cell dissociation in pancreatic cancer cells." (PMID 34808689, 2022). "In pancreatic cancer, CLDN1 can lead to TNF-alpha-dependent proliferation." (PMID 30519576, 2018). "Similar to our study, recent studies demonstrated that the CLDNs was frequently down-regulated in various cancers, for instance, the expression of CLDN1 was down-regulated in pancreatic cancer cells and that re-expression of CLDN1 reduced the invasive ability of these cells." (PMID 30349422, 2018). "The mechanism by which Cldn1 expression is increased in pancreatic cancer cells remains unclear." (PMID 40361399, 2025).
pancreatic cancer (continued). "Thus, investigating the precise role of Cldn1 in pancreatic cancer could aid in identifying new therapeutic targets and improving prognosis." (PMID 40361399, 2025). "Therefore, promoting the expression of CLDN1 may be an important factor in inhibiting the invasion and metastasis of pancreatic cancer cells." (PMID 40687428, 2025). "To examine the significance of Cldn1 expression in pancreatic cancer cells for malignancy, we established PK45H cells, which are poorly differentiated pancreatic cancer cells, utilizing a CRISPR/Cas9-based method for the stable knockout of Cldn1." (PMID 40361399, 2025). "Immunohistochemistry confirmed a proportional relationship between the Cldn1, DD, and AKR1B1 intensity scores in pancreatic cancer cells." (PMID 40361399, 2025). "For example, the knockdown of CLDN1 was shown to promote EMT and metastasis in pancreatic cancer via β-catenin signaling, indicating that maintaining CLDN1 expression can counteract EMT induction." (PMID 40687428, 2025). "PKCα downregulates claudin-1 via Snail- and MAPK/ERK-dependent pathways, which leads to decreased cell-cell adhesion during EMT in pancreatic cancer." (PMID 34354941, 2021). "AUC plots demonstrated that CLDN1 and CLDN18 represent potential predictors of thyroid cancer, and CLDN4 and CLDN18, predictors of pancreatic cancer." (PMID 29050243, 2017). "As a major component of tight junctions in epithelial cells, CLDN1 not only promotes EMT when its expression is suppressed but also promotes downstream target genes FAK and Paxillin phosphorylation, further enhancing pancreatic cancer migration and invasion." (PMID 40687428, 2025). "Within the same tissue, there was a trend toward Cldn1 expression in intermediate-to-poorly differentiated pancreatic cancers, even when Cldn1 expression was weak or absent in well-differentiated pancreatic cancers." (PMID 40361399, 2025). "A detailed observation of Cldn1 of pancreatic cancer cells in resected specimens revealed that the intensity of Cldn1 expression was not homogeneous within the same pancreatic cancer tissue." (PMID 40361399, 2025). "Claudin-1 and −7, tricellulin and marvelD3 are involved in EMT in pancreatic cancer cells." (PMID 27121055, 2016).
ulcerative colitis (25 papers, 2020 to 2025). An inflammatory bowel disease involving the mucosal surface of the large intestine and rectum. "For instance, increased expression of CLDN1 was observed in ulcerative colitis and Crohn’s disease and has been found to be associated with inflammation." (PMID 41321497, 2025). "Additionally, claudin-1 has been associated with several gastrointestinal diseases, including inflammatory conditions such as ulcerative colitis and Crohn’s disease." (PMID 39201334, 2024). "CLDN-1 may be a potential biomarker for ulcerative colitis susceptibility." (PMID 35571126, 2022). "Several studies have reported increased expression of claudin-1 and -2 and a reduction in claudin-3 and -4 expression in ulcerative colitis." (PMID 39334888, 2024). "Compared with the DSS group, DID treatment significantly increased the expression levels of ZO-1 and Claudin-1 in the colon tissue of DSS-induced ulcerative colitis mice." (PMID 39452928, 2024). "In ulcerative colitis, an inflammatory disease characterized by gut barrier dysfunction, claudin-1 protein expression was found to be upregulated." (PMID 39796069, 2024). "This study investigated the roles and regulation of the claudin-1, -2, -3, and -4 isoforms in the pathogenesis of ulcerative colitis, and the potential therapeutic effects of nobiletin." (PMID 39334888, 2024). "The downregulations of several “tightening” TJ proteins like claudin-1 and -4, together with an upregulation of claudin-2, were found to contribute to the barrier defect observed in ulcerative colitis." (PMID 35734166, 2022). "In ulcerative colitis in vivo models, it has been observed that the claudin-1 protein is significantly decreased in colonic tissue." (PMID 34827656, 2021). "Specifically, DHA has been shown to increase Cldn-1 expression in a mouse model of ulcerative colitis, in the intestinal cells of LPS-challenged piglets, and in TNF-alpha-challenged porcine epithelial cells." (PMID 34884896, 2021). "Expression of Claudin1 (CLDN1) has been shown to be increased in both high-grade dysplasia and ulcerative colitis-associated CRC tissue when compared to ulcerative colitis and normal tissue." (PMID 33937029, 2021). "The key inflammatory cytokine TNFα led to the increase in claudin-1 in IEC-18 cells, and increased expression of claudin-1 was observed in ulcerative colitis." (PMID 34573663, 2021). "Similarly, in patients with ulcerative colitis, expressions of Occludin, Claudin-1, and -4 are found to be reduced." (PMID 41031160, 2025). "Moreover, occludin protein expression was downregulated in the colorectal tissues of patients with ulcerative colitis (UC) and Crohn's disease, as was claudin-1 protein expression in the colon of patients with UC." (PMID 38368407, 2024). "Moreover, it has been observed that claudin-1/4 and occludin are downregulated in the intestinal epithelia of patients with ulcerative colitis." (PMID 36212959, 2022). "In addition, CLDN1 is widely expressed in the intestinal epithelium; increased expression of CLDN1 is observed in intestinal inflammatory disorders, such as Crohn’s disease and ulcerative colitis." (PMID 33784242, 2021). "In patients with ulcerative colitis, treatment with 1,25(OH)2D3 decreased claudin-1 protein levels in both inflamed and non-inflamed tracts." (PMID 39796069, 2024). "Research has repeatedly shown that the intestinal epithelial barrier is compromised in ulcerative colitis (UC) when ZO-1, Claudin-1, and Occludin, essential TJ proteins, are not expressed normally." (PMID 38201190, 2024). "Reduced expression of claudin-1 was observed in patients with inflammatory bowel disease (IBD) and irritable bowel syndrome (IBS), while an increase in claudin-2 was found in the inflamed epithelium of patients with ulcerative colitis (UC)." (PMID 37745643, 2023).
ulcerative colitis (continued). "In conclusion, our immunofluorescence and immunoblotting detection of claudins consistently demonstrates the suppression of claudin-1 and -4, the increase in claudin-2, and no change in the claudin-3 isoform in the present model of ulcerative colitis, all of which are reversed by nobiletin." (PMID 39334888, 2024).